REG1A (regenerating family member 1 alpha)
Description:
Might act as an inhibitor of spontaneous calcium carbonate precipitation. May be associated with neuronal sprouting in brain, and with brain and pancreas regeneration.
Synonyms: ICRF; REG; PSP; PTP; PSPS; PSPS1; P19
Tractability: Antibody: UniProt places it where antibodies can reach, with medium confidence; UniProt predicts a signal peptide or a membrane-spanning region; its Gene Ontology location is reachable by antibodies, with medium confidence.
Gene: Protein-coding gene on chromosome 2 (79,120,362 to 79,123,409, forward strand). Ensembl gene ENSG00000115386.
Subcellular location: Secreted
Pathways (Reactome):
Developmental Biology: Developmental Lineage of Pancreatic Acinar Cells
Gene Ontology:
Molecular function: growth factor activity; molecular function inhibitor activity; protein binding; hormone activity
Biological process: antimicrobial humoral immune response mediated by antimicrobial peptide; positive regulation of cell population proliferation; response to peptide hormone; signal transduction
Cellular component: extracellular exosome; extracellular region
Genetic constraint (gnomAD): Loss-of-function variants: 19 observed, 20.42 expected, observed/expected ratio (o/e) 0.93, 90% interval 0.65 to 1.37. The upper end of that interval is the gene's LOEUF score, 1.37, which puts it in group 5 of 6, group 1 being the genes least tolerant of losing a copy. Missense variants: 191 observed, 206.88 expected, observed/expected ratio (o/e) 0.92, 90% interval 0.82 to 1.04. Synonymous variants: 89 observed, 72.35 expected, observed/expected ratio (o/e) 1.23, 90% interval 1.03 to 1.47.
Homologues: Orthologues: macaque REG1A (93% identical), chimpanzee REG1A (88% identical), mouse Reg1 (72% identical), rabbit REG1A (70% identical), mouse Reg2 (66% identical), rat Reg1a (66% identical), zebrafish zgc:172053 (28% identical), zebrafish si:ch211-125e6.5 (28% identical), zebrafish si:dkey-241l7.4 (27% identical), zebrafish si:dkey-241l7.5 (27% identical), zebrafish lectin (26% identical), zebrafish si:dkey-241l7.2 (26% identical), and 13 more. Paralogues in human: REG1B (87% identical), REG3A (51% identical), REG3G (50% identical), REG4 (31% identical), CLEC19A (28% identical).
Diseases named in the same sentence as REG1A in open-access papers:
REG1A is named in the same sentence as 65 diseases in open-access papers, as found by Europe PMC text mining. Sharing a sentence is not in itself a finding about the gene and the disease. The quoted sentences say what the papers report.
Sepsis (24 papers, 2012 to 2026). Sepsis is defined as life-threatening organ dysfunction caused by a dysregulated host response to infection. "Besides sepsis, serum levels of REG1A and REG3A are increased in people with pancreatitis, as well as gastrointestinal pathologies, such as inflammatory bowel disease and colorectal carcinoma." (PMID 36387376, 2022). "Regenerating islet-derived protein (REG) 1A (aka pancreatic stone protein) and REG3A (aka pancreatitis-associated protein) are upregulated in humans with sepsis, pancreatitis, and gastrointestinal diseases, but little is known about this protein family in dogs." (PMID 36387376, 2022). "This parallels findings in humans, where patients with inflammatory bowel disease have only mildly higher REG3A concentrations, whereas patients with AP and sepsis often have markedly higher REG3A and REG1A concentrations in comparison with healthy volunteers." (PMID 40392915, 2025). "Pancreatic stone protein, also known as regenerating island-derived (or islet-derived) protein (REG) 1A, a protein primarily produced in the pancreas, has been investigated as a novel biomarker for sepsis in humans in the last decade." (PMID 40392915, 2025). "Therefore, we conclude that REG3E cannot discriminate between these diseases, and is by extension, in contrast to REG1A in humans, unlikely to be able to differentiate between sepsis and non-septic SIRS." (PMID 40392915, 2025). "Concentrations of REG1A can reliably distinguish sepsis from non-septic SIRS, correlate well with disease severity, and can predict development of sepsis and non-survival, performing at least as well as CRP and PCT in several studies." (PMID 40392915, 2025).
diabetes (10 papers, 2012 to 2025). "Reg-1α is expressed under normal and pathological circumstances, associated with diabetes, cancer, and inflammation." (PMID 35955718, 2022). "We therefore speculate that REG1A causes diabetes by destroying islet cells, whereas RUNX3 causes DKD by directly destroying vascular endothelial cells." (PMID 35937821, 2022). "For instance, PDAC and diabetes patients have higher serum levels of REG1A compared to healthy subjects, and REG3A is also increased in ductal fluid." (PMID 31696115, 2019). "Increased circulating serum levels of REG1A are manifested across different types of diabetes including type 1 (T1D), maturity onset diabetes of the young (MODY) and type 2 (T2D) indicative of β-cell apoptosis." (PMID 31696115, 2019). "These earlier findings demonstrated that PSP/reg1A gene expression was induced during apoptosis in in vitro and animal models of diabetes." (PMID 22808921, 2012). "We found that PSP/reg1A levels were significantly higher in the type 1 diabetes mellitus population (median = 13.52 ng/ml, IQR = 10.91-19.01 ng/ml versus median = 10.72 ng/ml, IQR = 8.94-12.54 ng/ml, p = 0.0007)." (PMID 22808921, 2012). "In situations where the amount of glycosylation is altered and calpains overactivated, such as neurodegenerative diseases or diabetes, calpain cleavage of Reg-1α would generate two new entities: i.e., a peptide of only four amino acids, and the Reg-1αΔN1−4 fragment." (PMID 35955718, 2022). "In contrast, REG1A was overexpressed in ATLANTIS under diabetes." (PMID 31696115, 2019). "Disruption of murine Reg1 (the ortholog of rat Reg1a) resulted in decreased proliferative capacity of pancreatic beta cells, whereas administration of recombinant rat Reg1a resulted in beta-cell regeneration and reversal of diabetes in rats after surgical resection of 90% of the pancreas." (PMID 24465846, 2014). "In the unhealthy population they co-occur with REG1A, REG1B, CPB1, and REG3A, all involved in diabetes mellitus and malignant neoplasms." (PMID 37021928, 2023). "We also demonstrated elevated serum levels of PSP/reg1A, the human homologue of PSP/reg, in human subjects with HNF1A-MODY and in subjects with type 1 diabetes mellitus, suggesting that the endocrine pancreas is the primary source of this signal." (PMID 22808921, 2012). "We analysed serum PSP/reg1A levels and correlated with clinical and biochemical parameters in subjects with HNF1A-MODY, glucokinase (GCK-MODY), and type 1 diabetes mellitus." (PMID 22808921, 2012). "Many of our dogs with pancreatitis had concurrent diseases, some of which, such as gastroenteropathies, renal and hepatic disease, or diabetes mellitus, may have contributed to the high REG3E concentrations in this group, as reported for REG1A in humans." (PMID 40392915, 2025). "Patients with type 1 diabetes mellitus also showed elevated PSP/reg1A levels independent of age or disease onset." (PMID 22808921, 2012). "Patients with type 1 diabetes mellitus also had elevated serum levels of PSP/reg1A compared to controls, however this was independent of the duration of diabetes." (PMID 22808921, 2012).
gastric cancer (10 papers, 2013 to 2024). A primary or metastatic malignant neoplasm involving the stomach. "The REG protein family is also known to be associated with gastric cancer development and Reg1α and Reg4 have been suggested as prognostic markers for advanced stomach cancers in man." (PMID 23899160, 2013). "In gastric cancer, Reg1α promoted angiogenesis via the classical Akt and Erk signaling pathways, while Reg3A enhanced cell viability and drug resistance in ovarian cancer by activating the Akt signaling pathway." (PMID 39857608, 2024). "In gastric carcinomas, there is limited data on the role of REG1A, despite reports of its downregulation through epigenetic methylation." (PMID 38414029, 2024). "Zhang and co-workers used an RNA-seq approach to identify that REG1A was downregulated in gastric carcinoma." (PMID 29484116, 2018). "Besides, in primary gastric epithelial cells, helicobacter and gastrin stimulated the expression of REG1α and accelerated the progression of gastric cancer." (PMID 37626036, 2023). "Conversely the most downregulated gene in diffuse gastric cancer subset is REG1A (fold change of −7.47), a tumor suppressor that, when overexpressed, reduces invasion and promotes apoptosis of gastric cancer cells, and that is typically downregulated in gastric cancer patients." (PMID 34012923, 2021). "REGIV and REG1A have also been shown to be elevated in gastric cancer and may serve as prognostic indicators." (PMID 24007603, 2013). "Knocking down REG1A (and REG3A) in gastric cancer cells leads to greater proliferation and infiltration whereas overexpression coincides with enhanced apoptosis." (PMID 31696115, 2019). "We identified REG1A, CHGA, TFF2, ATP4A and ATP4B to be downregulated in intestinal gastric cancer, and Rajkumar and co-workers found ATP4A and ATP4B to be downregulated in gastric tumor tissues compared to normal tissues." (PMID 29484116, 2018). "Using the top eight upregulated genes (SLPI, PLA2G2A, CXCL1, CCL20, REG1A, CLDN7, PI3, LGALS3) as a representative gene set for the high metabolic subcluster, we calculated the GSVA score of this gene set for each patient in the TCGA gastric cancer cohort." (PMID 38831933, 2024).
pancreatic cancer (9 papers, 2013 to 2025). "REG1A has been shown to be a prognostic indicator of pancreatic cancer, with higher levels of REG1A associated with poorer outcomes." (PMID 37322046, 2023). "REG1A, REG1B, and REG3A were reported to be increased in cancer ductal fluid, and REG1A was linked to pancreatic cancer." (PMID 37107224, 2023). "The illustration also indicates that age, sex, plasma CA19-9, creatinine, LYVE1, REG1B, TFF1, and REG1A have a positive correlation in the diagnosis of pancreatic cancer meaning that they are statistically significant predictors of pancreatic cancer diagnosis." (PMID 40269234, 2025). "In human pancreatic cancer cells, core 3 synthase significantly suppressed tumor growth and metastasis through downregulating the expression of several genes including REG1α." (PMID 37626036, 2023). "In another study, a neural network algorithm was employed to screen 140 datasets of individuals diagnosed with pancreatic cancer, for gene biomarkers in urine samples, namely REG1A/1B, LYVE1, TFF1, and CA19-9." (PMID 36358800, 2022). "In this study, we found significant elevations of Reg1A and Reg1B in the sera of pancreatic cancer patients in comparison to normal healthy subjects." (PMID 27788482, 2016). "The overexpression of the Reg1A gene in pancreatic cancer cells has been shown to result in accelerated cell proliferation and tumor growth, both in vitro and in vivo." (PMID 27788482, 2016). "In their study, Patel & Mukherjee66 developed a neural network model using four urine biomarkers (REG1A, REG1B, LYVE1, and TFF1) to predict locally progressed pancreatic cancer." (PMID 40269234, 2025). "Both REG1A and REGIII were also found elevated in plasma from a mouse model of pancreatic cancer." (PMID 24007603, 2013).
colorectal cancer (8 papers, 2017 to 2025). A primary or metastatic malignant neoplasm that affects the colon or rectum. "The REG1A gene encodes a protein that is secreted by the exocrine pancreas and is expressed in the normal colorectal mucosa and tumors, such colorectal cancer, pancreatic ductal adenocarcinoma." (PMID 29484116, 2018). "As well, upregulated mRNA expression of REG1A has been shown as an unfavorable prognostic marker in colorectal cancer and has been associated with peritoneal carcinomatosis." (PMID 29088818, 2017). "Knockdown of Reg1α has been shown to enhance the sensitivity of colorectal cancer cells to 5-FU, improving the efficacy of existing treatments." (PMID 39857608, 2024). "Moreover, METTL3 mediates the expression of REG1α in an m6A dependent manner to activate glycolysis process of colorectal cancer cells." (PMID 40097750, 2025). "REG1A, CK20, and MAP3K8 gene expression was shown to be related to early-onset colorectal cancer formation." (PMID 33507673, 2021).
pancreatitis (7 papers, 2013 to 2025). Inflammation of the pancreas. "REG1A encodes a protein that is secreted by the pancreas and associated with islet cell regeneration, diabetogenesis and pancreatic stone formation in pancreatitis." (PMID 39112965, 2024). "Additionally, REG1A and REG3A (also known as pancreatitis-associated protein or PAP) from the same protein family are high in people with pancreatitis, particularly severe acute pancreatitis (AP)." (PMID 40392915, 2025). "REG1A, a protein that is highly similar to REG1B has been implicated in pancreatitis, and other REG family members such as REGIV and hepatocarcinoma-intestine-pancreas/pancreatitis associated protein I (HIP/PAPI) have shown potential diagnostic utility for pancreatic cancer." (PMID 24007603, 2013). "Spontaneously occurring pancreatic stones, where REG1A was first discovered as PSP in humans, are extremely rare in dogs, despite pancreatitis being a relatively common disease in this species." (PMID 36387376, 2022).
inflammatory bowel disease (6 papers, 2019 to 2025). A spectrum of small and large bowel inflammatory diseases of unknown etiology. "REG1A is known to be antiapoptotic and is induced in the inflamed tissue in patients with inflammatory bowel disease (IBD)." (PMID 33502317, 2021). "DGE of the lower villus zone revealed that NEC epithelial cells exhibited substantial increase in the antimicrobial genes LCN2, REG1A, REG1B, and DMBT1, genes previously shown to be elevated in inflamed epithelium associated with inflammatory bowel disease (IBD)." (PMID 37205711, 2023). "Collectively, their findings suggest that the new proliferative factor REG1A, which is regulated by IL-6/IL-22-JAK-STAT3 signaling, may represent an attractive therapeutic target for patients with inflammatory bowel disease." (PMID 35432477, 2022). "REG1A and REG1B are upregulated in human colonic or gastric mucosa with inflammatory bowel disease (IBD) and ulcerative colitis (UC)." (PMID 31696115, 2019).
ulcerative colitis (5 papers, 2017 to 2024). An inflammatory bowel disease involving the mucosal surface of the large intestine and rectum. "One study reported the use of mucosal proinflammatory gene signatures (TNF, interleukin 1 alpha [IL1A], regenerating family member 1 alpha [REG1A], IL8, interleukin 1 beta [IL1B], and leukocyte immunoglobulin-like receptors A [LILRA]) in patients with ulcerative colitis." (PMID 39483464, 2024). "A recent study investigating the link between REG genes and IBD reported that REG1A, REG1B, and REG4 are overexpressed in the colon of Crohn’s disease patients, and that REG4 is overexpressed in the colon of ulcerative colitis patients." (PMID 29807746, 2018).
chronic pancreatitis (4 papers, 2016 to 2025). A chronic inflammatory process causing damage and fibrosis of the pancreatic parenchyma. "In humans, renal disease is also associated with higher REG1A concentrations, with values exceeding those of patients with acute or chronic pancreatitis within the same study." (PMID 40392915, 2025). "We also observed statistically insignificant elevations of Reg1A and Reg1B in the sera of chronic pancreatitis compared to normal controls." (PMID 27788482, 2016). "There were only slight elevations of Reg1A and Reg1B levles in the sera of chronic pancreatitis compared to the normal controls which were not statistically significnant (mid column)." (PMID 27788482, 2016).
colon carcinoma (4 papers, 2016 to 2025). "It should be noted that IL-22 stimulation of REG1A is based on the presence of IL-activatable elements of the REG1A promoter and may be mediated through STAT3 tyrosine phosphorylation as in colon cancer cells in vitro." (PMID 31696115, 2019).
type 1 diabetes (4 papers, 2012 to 2025). "For CD2 and CD3, the human genes of S100A9 (calcium binding protein A9) and IGHG1 (immunoglobulin heavy constant gamma 1) have previously identified as genes of interest as is the case with REG1A (pancreatic stone protein) for type-1 diabetes." (PMID 40893175, 2025).
colitis (3 papers, 2019 to 2025). Inflammation of the colon. "In their study, inducing REG1A expression in a DSS colitis mouse model promoted the recovery of the intestinal barrier." (PMID 40849632, 2025). "We observed a universal upregulation of REG1A/REG1B across subtypes of UC, including both active extensive colitis and inactive extensive colitis." (PMID 32731480, 2020).
diabetic kidney disease (3 papers, 2022 to 2024). Progressive kidney disorder caused by vascular damage to the glomerular capillaries, in patients with diabetes mellitus. "Consistent with this interpretation, Reg-1a has also been proposed as a marker of diabetic nephropathy." (PMID 37883447, 2023). "The expression of REG1A has been demonstrated to be significantly increased in blood samples of patients affected by diabetic kidney disease (DKD) and correlated with urinary albumin/creatinine ratio, suggesting a role as a biomarker for the risk of developing DKD." (PMID 39449501, 2024).
bladder cancer (2 papers, 2023 to 2024). "This is consistent with previous work showing that REG1A overexpression was associated with invasion and poor prognosis of colorectal and bladder cancer patients, while its inhibition impaired cancer cell migration." (PMID 38414029, 2024).
MODY (2 papers, 2013 to 2015). "ROC analysis on all data with the exclusion of the two patients with extreme hsCRP levels demonstrated that PSP/reg1A showed 90% sensitivity in identifying HNF1A-MODY patients, but with reduced specificity (67%)." (PMID 23803251, 2013).
neuroendocrine carcinoma (2 papers, 2023 to 2025). A malignant neuroendocrine neoplasm composed of cells containing secretory granules that stain positive for NSE and chromogranin. "Additionally, REG1A and CPA1 show utility in diagnosing mixed pancreatic acinar cell carcinoma/acinar-neuroendocrine carcinoma; notably, we show that CPA1 has the highest reduction in PanNETs, which is consistent with the absence of CPA1 immunohistostaining in PanNETs." (PMID 40217502, 2025).
pancreatic ductal adenocarcinoma (2 papers, 2018 to 2021). An infiltrating adenocarcinoma that arises from the epithelial cells of the pancreas. "Regenerating proteins, including REG1A and REG1B, promoted acinar-to-ductal metaplasia and acted as novel diagnostic and prognostic markers in pancreatic ductal adenocarcinoma." (PMID 34055623, 2021).
Alzheimer disease (1 paper, 2022). A progressive, neurodegenerative disease characterized by loss of function and death of nerve cells in several areas of the brain leading to loss of cognitive function such as memory and language. "Reg-1α/lithostathine, a protein mainly associated with the digestive system, was previously shown to be overexpressed in the pre-clinical stages of Alzheimer’s disease." (PMID 35955718, 2022).
breast carcinoma (1 paper, 2024). "REG1A (Regenerating Family Member 1 Alpha) has been implicated in various cancers, including breast cancer." (PMID 39000413, 2024). "Hallmark Il6 Jak Stat3 Signaling (Overlap Genes: INHBE, REG1A): This signaling pathway is involved in inflammation and immune responses and has been linked to breast cancer progression and metastasis." (PMID 39000413, 2024).